CD80 (CD80 molecule)
Diseases named in the same sentence as CD80 in open-access papers (continued):
Sharing a sentence is not in itself a finding about the gene and the disease.
autoimmune disease (48 papers, 2006 to 2025). A disorder resulting from loss of function or tissue destruction of an organ or multiple organs, arising from humoral or cellular immune responses of the individual to their own tissue constituents. "Fusion proteins associated with CD80 can also be utilized in the treatment of autoimmune diseases, including rheumatoid arthritis (RA), renal transplant rejection, psoriatic arthritis (PsA), and others." (PMID 39575257, 2024). "The soluble form of CTLA-4, capable of binding CD80, is implicated in the pathogenesis of several autoimmune diseases, in which sCTLA-4 is able to inhibit early T-cell activation by blocking the interaction between CD80 and the costimulatory receptor CD28." (PMID 37483633, 2023). "Thus, abnormal expression levels and functional alterations of CD80 are closely associated with various immune-related disorders, including autoimmune diseases, allergic reactions, and tumor immune evasion." (PMID 38361527, 2023). "Our data therefore suggest new contexts in which CD80 could be implicated in autoimmune diseases and cancer." (PMID 33488578, 2020). "Our analysis suggests that the decreased CD80/CD86 ratio may be linked to the full development of the autoimmune disease, whereas the overexpression of CD40 pre-dates the occurrence of overt autoimmunity and may therefore be involved in its pathogenesis." (PMID 16507174, 2006). "Specifically, autoimmune-associated B cells (ABCs; defined as CD19+CD11c+) are a subset of potent APCs in autoimmune diseases, expressing high levels of CD80/CD86 and MHC class II." (PMID 41497588, 2025). "This review mainly focus on the role of CD80 in the immune system, as well as the research progress on the application of CD80-related immunopharmaceuticals in the treatment of tumors and autoimmune diseases." (PMID 39575257, 2024). "The abnormal expression of CD80 in autoimmune diseases makes CD80 a potential and effective target for autoimmune diseases." (PMID 39575257, 2024). "An anti-CD80 antibody blocking PD-L1/CD80 cis-interactions augmented PD-L1/PD-1 interactions and alleviated autoimmune disease." (PMID 37928556, 2023). "Okazaki and colleagues have even demonstrated that disrupting cis–CD80/PD-L1 interactions alleviates multiple autoimmune disease models." (PMID 37267353, 2023). "The therapeutic efficacy of inhibiting DC:T-cell interactions in multiple autoimmune diseases has already been shown using Abatacept which binds to CD80/86 on DCs, preventing the co-stimulatory signal required for T-cell activation." (PMID 37232738, 2023). "B cells are believed to be important APCs in the pathogenesis of autoimmune diseases and express CD80/CD86 after activation; however, relatively little is known about the effect of CTLA-4-Ig on B cells." (PMID 32228715, 2020). "Despite their structural similarities, CD80 and CD86 make distinct contributions to the development of pathogenic T cells in autoimmune diseases and protective T cells in infectious diseases." (PMID 27292320, 2016). "CD40 engagement in both T or B cells leads to the production of cytokines, such as IL-12, IL-2, TNF-α, IFN-α, and CD80, developing an environment which is conducive to autoimmune diseases." (PMID 23533546, 2013). "In addition, abnormal CD80 is also closely related to autoimmune diseases, which makes targeting abnormal CD80 molecules in autoimmune diseases an option for the treatment of autoimmune diseases." (PMID 39575257, 2024). "Monoclonal antibodies against CD80 also play an important role in autoimmune diseases." (PMID 39575257, 2024). "The fusion protein targeting CD80 also holds great promise for application in autoimmune diseases." (PMID 39575257, 2024). "In autoimmune diseases, CD80 can also regulate autoimmune diseases by modulating immunity." (PMID 39575257, 2024).
autoimmune disease (continued). "Signals transduced by CTLA-4 following CD80/86 binding, and PD-1 following PD-L1 binding inhibit the “hyperactivation” of T cells and are important in preventing abnormal immune responses commonly seen in autoimmune diseases." (PMID 36969071, 2023). "Conversely, insufficient CD80 costimulation during antigen presentation may result in tolerance induction, and inhibiting CD80 costimulation has shown the potential to hinder the progression of autoimmune diseases in multiple animal models." (PMID 38159255, 2023). "We generated designer EVs to modulate T cells in the context of type 1 diabetes, a T cell–mediated autoimmune disease, by engineering a lymphoblast cell line, K562, to express HLA-A*02 (HLA-A2) alongside costimulatory CD80 and/or coinhibitory programmed death ligand 1 (PD-L1)." (PMID 37267353, 2023). "Our analyses suggest that the defect of CD80 in NZM2410 and NZB-W/F1 mice, which closely resembles the costimulatory defect found in DCs from humans with systemic lupus erythematosus, is linked to the autoimmune disease." (PMID 16507174, 2006). "Therefore, enhancing the efficacy of CAR-T by CD80 stimulation of CD28 may promote the progress of CAR-T immunotherapy in autoimmune diseases." (PMID 39575257, 2024). "In addition, the application of switch CAR/CCR T cell strategy to other areas such as B cell-mediated autoimmune diseases is also conceivable, as autoreactive B cells clusters with the most recently activated class-switched mBC (memory B cell) phenotype exhibit high CD80 and CD86 expression." (PMID 38340727, 2024). "CD80 may provide a new direction for the prevention and treatment of other autoimmune diseases." (PMID 39575257, 2024). "In autoimmune diseases, DCs as professional APCs have a potent ability to trigger naive T-cell reaction and activate an autoreactive response, and decreasing CD80/86 prevented T-cell activation and Th-cell differentiation by inhibiting the costimulatory second signal." (PMID 31427972, 2019). "We therefore propose that the decreased ratio of CD80 to CD86 in lupus DCs may be linked to the full development of the autoimmune disease, whereas the overexpression of CD40 may be important in the pathogenesis of this autoimmune disease." (PMID 16507174, 2006). "It indicates that blocking the CD80/CD28 costimulatory signaling pathway with 4E5 is a very promising strategy to slow the progression of lupus-like diseases and other autoimmune diseases." (PMID 39575257, 2024). "Dysregulation of CD80 and/or CD86 occurs in diverse autoimmune diseases, including EAE, RA, and EAU." (PMID 36739434, 2023). "This suggests that the expression of both CD80 and PD-L1 in APC enhances autoimmune diseases, including RA." (PMID 36180526, 2022). "PD-L1+/CD80- pDCs, referred to as P1, were found to be specialized in the production of IFN-Is and prevalent in patients with IFN-I-mediated autoimmune diseases." (PMID 33995415, 2021). "In contrast to the function of CD80/CD86, CTLA-4 can transmit an inhibitory signal to T cells to avoid some autoimmune diseases in normal people." (PMID 32793247, 2018). "PU.1 plays a crucial role in the regulation and expression of CD80, CD86, and cells in the hematopoietic system and it can also block several autoimmune diseases and even induce donor-specific tolerance to allograft." (PMID 26509179, 2015). "On the one hand, recent data shows that CD80 favorably binds CTLA-4 and as a result, provides critical suppression of T cell responses protecting from autoimmune diseases." (PMID 25505551, 2014). "B cell CD80 expression was higher in women with HAM/TSP, underscoring that immune markers can reflect the female predominance observed in most autoimmune diseases." (PMID 24472094, 2014). "In vivo studies using anti-CD80 mAbs and anti-CD86 mAbs have suggested that CD80 and CD86 differentially regulate the development of autoimmune disease." (PMID 22997525, 2012).
autoimmune disease (continued). "All these molecules exist as a soluble form and could interact with their receptors on monocytes: for example, sCTLA-4 could interact with CD80/86 and thereby prevent the binding with CD28 and T cell activation, as shown in autoimmune diseases." (PMID 39159266, 2024). "CD80 can promote T-cell differentiation to Th1, while CD86 can induce Th2-mediated humoral immune responses, which are crucially involved in the immune response of autoimmune diseases." (PMID 34925005, 2021). "Abnormal expression of CD80 and CD86 may lead to the initiation and exacerbation of autoimmune diseases." (PMID 32149157, 2020). "In addition, while CD80 and CD86 have been reported to play distinct functional roles in animal models of autoimmune disease, their individual contributions to shaping downstream T cell responses remain incompletely understood." (PMID 27898740, 2016). "Abatacept, a CTLA-4Ig costimulatory blockade that interferes with CD28 on T cells binding to CD80/CD86 on APCs, has shown efficacy in clinical trials for RA (which has become one of the established treatments), psoriatic arthritis, and juvenile idiopathic arthritis, among other autoimmune diseases." (PMID 38567291, 2024). "In other autoimmune diseases, there is no relevant research on CD80-related vaccines." (PMID 39575257, 2024). "In this context, 111In-DOTA-belatacept could serve as a research tool to study the approach of targeting CD80/CD86-rich APCs in atherosclerosis and possibly other inflammation-related diseases such as cancer, autoimmune disease, and rejection after organ transplantation." (PMID 26728358, 2016). "It has been shown that increased expression of CD80 and CD86 may be involved in the presentation of autoantigens and hyperactivation of T cells, in which the immune system attacks normal tissues and cells in the body, resulting in an exaggerated immune response in autoimmune diseases." (PMID 38361527, 2023). "However, in autoimmune diseases, the superior affinity of CTLA4 for its ligands led to the use of a CTLA4-immunoglobulin fusion protein (CTLA4-Ig) as an inhibitor of immune responses in vivo; the rationale being that it would bind to CD80 and CD86 and block their interaction with CD28." (PMID 26942414, 2017).
glioma (41 papers, 2011 to 2025). A benign or malignant brain and spinal cord tumor that arises from glial cells (astrocytes, oligodendrocytes, ependymal cells). "Furthermore, expression of regulators of mt-rRNA modification was associated with major moieties associated with immune checkpoints in glioma, especially PD-L1, PD-1, CD80, CD274, TIM3, and IDO1." (PMID 34566979, 2021). "The results showed connections between PLK3 and PD-1, and between PD-L1 and CD80, which revealed strong correlations among PD-1, PD-L1, and CD80 in whole-grade glioma, LGG, and GBM." (PMID 39866232, 2025). "The results of our investigation showed a strong relationship between the expression of SMARCAL1 and several immune checkpoint genes, including CD276, NRP1, TNFSF4, CD40, CD200, and CD80 in Glioma, LUAD, LIHC, KIRC, and UCEC." (PMID 39994264, 2025). "APCs in gliomas express less of the costimulatory ligands CD80 and CD86, which inhibits T-cell activation." (PMID 39452154, 2024). "The univariate Cox regression showed that the expression levels of PD-L2, TIM3, CD80, CD86, CD155, and CIITA were risk factors for glioma in all glioma population and the HGG population." (PMID 33996602, 2021). "In microglia sorted from rat C6 gliomas, genes characteristic for M1 activation: Tlr2, Tlr4 and Il18, Cd80, Il12a, Il15 were significantly downregulated." (PMID 29242629, 2017). "Active glioma Tregs can bind to CD80/CD86 via CTLA-4, suppressing T cell activity." (PMID 40071070, 2025). "In addition, immunosuppressive molecules such as PD-L1, TIGIT and CD80, which are expressed at increased levels on glioma cells, also negatively regulate the interaction between antigen-presenting cells and T cells." (PMID 36845098, 2023). "In addition, glioma cells also lack B7.1/2 (CD80/CD86) co-stimulatory molecules, but overexpress B7-H1 (or PD-L1) co-inhibitory molecule for T cells." (PMID 31225500, 2019). "However, it has been reported that glioma cell lines-derived exosomes lack antigen-presentation and the surface co-modulatory machinery CD80 and CD86 able to cross-react with CD28." (PMID 28107450, 2017). "An important common factor in T cell anergy is the lack of significant expression of co-stimulatory ligands such as CD28, CD80 and CD86 during antigen contact, which has been found in gliomas and in various mouse tumor models." (PMID 38275375, 2023). "Based on the TCGA and CGGA datasets, we proved that PTX3 positively correlated with CD276, CD274, PDCDL1LG2, HAVCR2, CD80, IDO1, and PDCD1 in pan‐glioma, GBM, and LGG." (PMID 35855654, 2022). "Thus, targeting CD80 may become an attractive strategy in immunotherapy for glioma." (PMID 35928223, 2022). "The GASC score was positively correlated with PD-1, PD-L1, PD-L2, TL1A, TIM3, Galactin-9, CTLA-4, CD80, CD86, CD155, LAG3, and CIITA in all glioma population and the HGG population." (PMID 33996602, 2021). "It has been reported that one potential mechanism of immune paralysis is low expression of MHC-I, MHC-II, CD80, and CD86 in glioma cells, which prevents normal antigen recognition." (PMID 28641579, 2017). "Elevated expression of CTLA-4 is observed in samples of high-grade gliomas, and this is attributed to the absence of CD80/86 co-stimulatory molecule expression." (PMID 39452154, 2024). "Through analysis of glioma samples in the CGGA and TCGA databases, we found that CDCA7 expression level was significantly correlated with tumor-related immunosuppressive molecules, including CD80, CD276, CD28, PDCD1LG2, and TNFSF4." (PMID 37510310, 2023). "Correspondingly, it showed that CD101 expression could potentially interact with numerous immune-relevant genes, including CD276, CD274, CD80, CTLA4, and PDCD1, implying an immunoregulatory role of CD101 in the glioma immune microenvironment." (PMID 35350788, 2022).
glioma (continued). "This has been confirmed by in vitro analyses showing induction of MHC class II molecules, CD80, CD86 and IL-12 in co-culture experiments of DCs and PDT-treated mouse tumour cells or DCs and acid-eluted material from PDT-treated C6 rat glioma cells." (PMID 21863026, 2011). "CLIC4 expression levels were positively correlated with specific markers of macrophages (CD80, CD86, MRC1), neutrophils (FCGR3A, FCGR3B), eosinophils (SIGLEC8, IL3RA), T cells (CD3D, CD4), CD8+ T cells (CD8A, CD8D), NK cells (NCAM1), and B cells (CD19) in glioma." (PMID 39595145, 2024). "Glioma-infiltrating microglia/macrophages from postoperative tissue samples of glioma patients expressed surface MHC-II but lacked the expression of the co-stimulatory molecules CD86, CD80, and CD40, which are critical for T cell activation." (PMID 40281508, 2025). "Glioma-associated macrophages and microglia produce low levels of pro-inflammatory cytokines and lack expression of key molecules involved in T-cell co-stimulation, such as CD86, CD80, and CD40, indicating that they may be negative inducers of T-cell response in glioma." (PMID 37543576, 2023). "The treatment with CMs from glioma cells resulted in elevated expressions of M2-macrophage markers CD206 and CD163, while showing no significant alterations in the M1-macrophage markers CD80 and CD86." (PMID 38576043, 2024).
Sepsis (41 papers, 2009 to 2025). Sepsis is defined as life-threatening organ dysfunction caused by a dysregulated host response to infection. "Studies have demonstrated that DC-related sepsis survival is associated with the expression of co-stimulatory molecules CD80 and CD86." (PMID 37434129, 2023). "In murine models of graft arterial disease and sepsis, CD80 is associated with proinflammatory cytokine stimulation, while CD86 plays a protective role mediated through IL-4 or IL-10 production." (PMID 24472094, 2014). "Specifically, sepsis was associated with an increase in CD80 expression, while there appeared to be a downregulation of constitutive CD86 expression." (PMID 19672303, 2009). "Our group and others have previously demonstrated that sepsis is associated with marked an increase in CD80 expression and a loss of constitutively expressed CD86 in mice." (PMID 19672303, 2009). "Similar findings were shown with combined blockade or deletion of CD80/86 in the same murine model of sepsis." (PMID 38633258, 2024). "As proof of concept, a translational study in LPS-induced porcine sepsis and human sepsis described that enhanced CD80 expression on podocytes was responsible for increased proteinuria." (PMID 37542608, 2023). "We observed the identical trend regarding the protein expression of mregDC marker genes, including CCR7, CD274 (PD-L1), and CD80, which were consistently upregulated and enriched at 24 h after sepsis." (PMID 35832091, 2022). "For example, CD23, CD95, and CD80 expression on B cells have been identified as biomarkers in sepsis prognosis." (PMID 27598216, 2016). "The number of CD80+ macrophages was significantly higher in the sepsis group compared with the control group (P<0.01)." (PMID 25244356, 2014). "Another evidence of the differential function of CD80/CD86 was a study demonstrating that CD80−/− mice had improved survival in a cecal ligation and puncture sepsis model when compared to wild-type or CD86−/− mice." (PMID 24367573, 2013). "Similar to mice, humans with sepsis exhibit a loss of CD86 and upregulation of CD80 on circulating monocytes." (PMID 19672303, 2009). "While our data provide strong evidence for a predominant role for CD80 in regulation of lethal inflammation in sepsis, the role for CD86 remains conflicted." (PMID 19672303, 2009). "We first wished to establish that CD28 was serving as the predominant ligand for CD80 or CD86 engagement in sepsis." (PMID 19672303, 2009). "Future therapeutic strategies for blockade of the CD80/86 system in sepsis should focus on direct inhibition of CD80." (PMID 19672303, 2009). "Moreover, combined plasma filtration and adsorption resulted in reduced endotoxemia, reduced CD80 in the urine, and prevented proteinuria in both experimental and clinical sepsis." (PMID 37542608, 2023). "Therefore, the goal of this study was to determine the individual contribution of CD80/86 family members in regulating inflammation in sepsis." (PMID 19672303, 2009). "However, the preponderance of studies analyzing the role of CD28 and/or its ligands CD80/86 in models in which the recipients used are immunologically naïve have demonstrated that deleting or antagonizing CD28 signaling results in improved sepsis mortality." (PMID 38633258, 2024). "CD80 and CD86 molecules played a differential role in a mouse sepsis model after caecal ligation and puncture (CLP)." (PMID 38355547, 2024). "sPLA2 can enhance the expression of CD86, CD80, CD83, and CD40 on the surface of DCs, promote DC maturation, and improve the prognosis of sepsis (ClinicalTrials.gov ID NCT00034476)." (PMID 38816685, 2024). "Sepsis is a condition that can result in multiple organ failure, leading to fatal outcomes, and the interaction of PD-1/PD-L1 with CD80, PI3K/Akt pathway, or STAT1 molecules plays an important role in the mechanism of sepsis-induced organ dysfunction." (PMID 38193090, 2023).